CASP8 (caspase 8)
Diseases named in the same sentence as CASP8 in open-access papers (continued):
Sharing a sentence is not in itself a finding about the gene and the disease.
cancer (continued). "Davallic acid, as shown in the present study, suppressed cell viability and induced apoptosis in the A549 cancer cells via increased ROS expression, enhanced release of cytochrome c, and induction of caspase-3, caspase-8, and caspase-9 expression." (PMID 23117433, 2012). "And it activated the extrinsic apoptosis pathway via caspase 8 by binding to its receptors on the surface of cancer cells." (PMID 23122182, 2012). "On the other hand, the effect of Res involves Caspase-8/Caspase-3 signaling and induction of apoptosis via the death receptor pathway in several cancer cell lines." (PMID 22218562, 2012). "The hubs also include RB1, BCL2, AKT1, CDK2, CASP8 which are involved in mechanisms of apoptosis, to which cells are known to acquire resistance in all types of cancers." (PMID 23166660, 2012). "In conclusion, in this study we affirmed that davallic acid obtained from D. divaricata Blume induced cell death in lung A549 cancer cells, playing an important role in apoptosis induction via caspase-3, caspase-8, and caspase-9 activation." (PMID 23117433, 2012). "Cellular FLICE-inhibitory protein (c-FLIP) is a truncated form of caspase-8 that has been shown to play a critical role in the development of resistance to therapeutics in cancer cells by inhibiting apoptosis mediated by death receptor signaling." (PMID 23028678, 2012). "Evidence showed that TNFAIP8 expression was upregulated by TNF-α induced NF-κB pathway activation in cancer cell lines, which can inhibit caspase-8 and reduce apoptosis." (PMID 22666399, 2012). "Caspase-3 and caspase-7 are key effector molecules known to induce apoptosis in variety of cancer cells by amplifying the signal from initiator caspases, such as caspase-8 or caspase-10." (PMID 22363450, 2012). "We found that, as a consequence of the EGFR inhibition, CL4 strongly inhibits the anti-apoptotic STAT3 and induces cell death selectively in EGFR-positive cancer cells by activation of caspase-3, caspase-8 and PARP." (PMID 21915281, 2011). "Bcl-2 levels are normally up-regulated in cancer cells as a means to safeguard them from apoptosis induction; this protein is also downstream of caspase-8." (PMID 21234313, 2011). "As an extension to these earlier observations, the current study demonstrates that in cancer cells that have become resistant to chemotherapy, the N-terminus of caspase 8 interacts instead with Bcl2 to restrict apoptosis." (PMID 22069448, 2011). "In this study, we demonstrate that Bcl2 and caspase 8 interact in cancer cells that have become refractory to therapy, thus providing another mechanism by which Bcl2 promotes survival and drug resistance." (PMID 22069448, 2011). "The apoptotic signaling pathway is inactivated in most cancer cells, including a group of proteases such as caspase-8 and caspase-3 that cross-talk with EGF survival signaling network." (PMID 21617769, 2011). "Epigenetic silencing of caspase-8 has been reported for several different cancer cells and caspase-8 re-expression can restore TRAIL-mediated killing." (PMID 20967281, 2010). "There is evidence of increased expression of caspase-8 in several types of cancer including colorectal and rectal, gastric, pancreatic, and breast cancers." (PMID 20808443, 2010). "Caspase-8 and -10 genes are located at the genomic locus 2q33-34, a region frequently affected in cancer." (PMID 24281211, 2010). "In gastric cancer, 8% of samples contained caspase-8 mutants, remarkably all of them in advanced carcinomas." (PMID 24281211, 2010). "As a first step, we examined activity levels of the extrinsic apoptotic initiator, caspase-8, and intrinsic apoptotic initiator caspase-9 levels in carcinoma cells secreting varying amounts of CXCL12 (Hi, Med, Low)." (PMID 20877573, 2010). "We transduced cancer cells to overexpress crmA which inhibits initiator caspases including caspase-1 and caspase-8 in the death-receptor pathway, or Bcl-2, a well-known inhibitor of multiple caspases in the mitochondrial pathway." (PMID 19247489, 2009).
cancer (continued). "Caspase-8 can be activated by HDAC inhibitors through the death receptors in several cancer cell lines." (PMID 17156483, 2006). "5-Aza-2′-deoxycytidine also increased expression of many other genes in cancer cells, such as caspase-8 and hMLH gene." (PMID 15798770, 2005). "One inhibitor of the TRAIL signalling pathway is FLIP, which structurally resembles caspase 8 and can act as an inhibitor of apoptosis when highly expressed in certain cancers." (PMID 12865931, 2003). "Our results indicate that the top credible causal set variant rs3769823 likely influences expression of CASP8 and FLACC1 in a cell-type specific manner and may be a relevant functional variant for multiple cancers associated with this locus." (PMID 41542517, 2026). "It has been discovered that the disruption of initiator caspase-8 and caspase-9 expression or function may play a role in the development or progression of cancer, and that their inactivation may increase resistance to existing therapeutic strategies." (PMID 40728967, 2025). "Finally, it is important to recognize that other E3 ubiquitin ligases, such as Cullin 7 (CUL7), can block caspase-8 degradation to enable cancer survival." (PMID 39996713, 2025). "In addition, studies have shown that ginsenoside CK can inhibit the activity of AKT1 in cancer cells, thereby increasing the expression levels of the apoptotic proteases Caspase-3, Caspase-8, and Caspase-9, and inducing apoptosis in cancer cells." (PMID 40422575, 2025). "The expected cytotoxic activity against cancer cells may be based on various mechanisms, e.g., enhancement of the process of apoptosis, stimulation of caspase 3 and caspase 8 or stimulation of TF NF kappa B/TF factor." (PMID 40572628, 2025). "Notably, the MYC, E2F2 and CASP8 genes, which are important regulators of the cell cycle and apoptosis and have previously been implicated in HPV-related processes or cancer, were identified as common trans-interaction sites in both the HiC and 4C datasets." (PMID 40892869, 2025). "Next, we explored whether CD8+ T cell–derived CD40L-CD40 signaling similarly triggers cytotoxicity in human cancer cells through caspase-8 activation." (PMID 40397730, 2025). "Quercetin could induce apoptosis via both intrinsic and extrinsic pathways by upregulating the expression of caspase-3, caspase-8, and caspase-9 in cancer cells." (PMID 40427691, 2025). "Specifically, we evaluated the influence of JTT on lymphocyte viability and immunophenotype in cancer patients, determined the optimal in vitro culture conditions and dosage, and examined its regulatory effects on Jurkat T cell apoptosis through caspase-8 and caspase-3 activation." (PMID 41304903, 2025). "Elevated ROS levels not only directly impair tumor cell viability but also sensitize cancer cells to apoptosis by activating caspase-8 and mitochondrial translocation of truncated BH3 Interacting Domain Death Agonist (tBID), especially under nutrient-deprived conditions." (PMID 41163402, 2025). "Src can directly phosphorylate Caspase-8 on Y380 and this phosphorylation impinges on Caspase-8 enzymatic activity, preventing its apoptotic canonical function, therefore justifying the high levels of Caspase-8 in cancer cells." (PMID 41053176, 2025). "Next, we examined the expression level of caspase-10, which is a paralog of caspase-8, is also involved in the death receptor pathway of apoptosis and was found in our transcriptomic data to be activated by ActD + Nut3a in various cancer cell lines." (PMID 39068622, 2024). "Caspase-8 expression in tumor cells varies across different cancer types." (PMID 39625520, 2024).
cancer (continued). "In HCC, the enzymatic activity of caspase-8 may be suppressed, which allows cancer cells to undergo apoptosis." (PMID 39726605, 2024). "GSDMC/caspase-8 mediates a non-canonical pyroptosis pathway in cancer cells, causing tumor necrosis." (PMID 39723212, 2024). "Therefore, it is of great importance to selectively target caspase-8, to further regulate its role in promoting and inhibiting cancer, and to study its involvement in PANoptosis." (PMID 38877579, 2024). "In summary, our findings suggest that BTZ’s potential anti-cancer efficacy could be largely attributed to its influence on the caspase-8-Bid-Bax/Bcl-2 mitochondrial pathway." (PMID 38724504, 2024). "Leveraging its central role in apoptotic regulation, CASP8 stands out as a promising therapeutic target, prompting the exploration of strategies to restore or enhance its activity for interventions that induce apoptosis in cancer cells." (PMID 39555097, 2024). "Further investigations may establish whether sFasL shed by cancer cells may account for the increased caspase-8 activity observed in our assays upon endocytosis inhibition (mechanical or chemical) even in the absence of exogenous sFasL." (PMID 38909035, 2024). "Consequently, a comprehensive understanding of the roles and regulatory mechanisms of caspase-8 in the context of HCC is essential for crafting impactful treatment strategies aimed at combating this cancer." (PMID 39726605, 2024). "Olaparib could increase death ligand-induced caspase-8 cleavage in cancer cells and modulate pyroptosis in the mouse model of Huntington’s disease." (PMID 37883181, 2024). "Together, Caspase 3, Caspase 8, and Caspase 9 play critical roles in mediating apoptotic cell death through both intrinsic and extrinsic pathways, highlighting their importance as therapeutic targets for cancer treatment." (PMID 38600497, 2024). "However, strong or accumulated ER stress induces apoptotic cell death via the activation of the CHOP-DR4/5-caspase-8/9-caspase-3 axis in various cancer cell lines, indicating a potential strategy for tumor therapy." (PMID 38140352, 2023). "Interestingly, from this analysis, we observed that Caspase-8 can be either pro- or antitumor, but rarely “neutral”, highlighting again the importance of this protein in cancer progression." (PMID 37444381, 2023). "In addition, both caspase-3 and caspase-8 were elevated in HK1 treated with BinB, indicating that apoptosis induction is the cytotoxic mechanism underlying the cancer cell death upon Bin treatment." (PMID 37104235, 2023). "But, to our knowledge, caspase-8 has not previously been associated with outcome for cancer patients." (PMID 36945037, 2023). "Both cleaved-caspase 8 and cleaved-caspase 9 activate caspase 3 to form cleaved-caspase 3, which in turn degrades the DNA repair-associated protein PARP and induces apoptosis in cancer cells." (PMID 36674931, 2023). "It is likely that Casp8 malfunction leads to ICD in cancer cells, which may provoke an adaptive immune response, facilitating CD8+ T cell infiltration and inducing an inflamed (hot) TME, which in turn improves the efficacy of ICB immunotherapies." (PMID 36635765, 2023). "Since CASP8 is the downstream target of the FASL-initiated apoptotic cascade, its loss could prevent cancer cells to undergo apoptosis." (PMID 37277866, 2023). "Finally, avoidance of apoptosis is a typical characteristic of cancer, including BC; therefore, BCL2-associated X-protein (BAX) and caspase-8 (CASP8), which participate in intrinsic and extrinsic apoptotic pathways, merited further investigation." (PMID 37264344, 2023). "Caspase-8 is a crucial player in extrinsic apoptosis, with downregulated activity in cancer." (PMID 37153540, 2023).
cancer (continued). "Moreover, Fas/caspase-8 pathway activation was demonstrated in melanoma and human gastric (KATO III) and colon (HCT-116) cancer cells where CUR also caused PARP-1 cleavage and caspase-3 activation." (PMID 36836619, 2023). "It was indeed reported that Beclin-1, but also ATG5 and ATG3, are caspase-8 substrates in vitro, and that after death receptor activation in several cancer cells, the subsequent downregulation of autophagic flux is partly due to caspase-8-dependent cleavage of these autophagic proteins." (PMID 36418547, 2023). "The interplay between FLIP and Caspase-8 in cancer has been largely reviewed elsewhere." (PMID 37444381, 2023). "Caspase‐8 (CASP8) is a key protein of cross‐talk signaling in a variety of cancers." (PMID 36533709, 2023). "Caspase-8 and -9 are other members of the caspase family and their major role in the process of the induction of apoptosis in various cancer cells in in vitro and in vivo either solely or in accompanying with caspase-3 has been demonstrated by prior researches." (PMID 36976217, 2023). "Altogether, this evidence stresses an under-researched connection between Caspase-8 and the ability of cancer cells to sense DNA damage and arrest the cell cycle, which opens the possibility to further understand the mechanisms that help cancer combat genotoxic stress and progress undisturbed." (PMID 37444381, 2023). "In cancer, the role of Caspase-8 in the promotion of inflammation is still controversial." (PMID 37444381, 2023). "Using HeLa cells as a model, the authors confirm that cancer cells lacking Caspase-8 are deficient in proper cell division." (PMID 37444381, 2023). "The observation that RTKs are commonly deregulated in cancer, along with their well-known role as Src activators, suggests the hypothesis of crosstalk between RTKs aberrant signaling and the modulation of Caspase-8 function in cancer." (PMID 37444381, 2023). "Indeed, CASP8 is an important switch for the activation of apoptosis and pyroptosis, and shows pleiotropic effects in cancer development." (PMID 35928267, 2022). "In addition, TUFM depletion promoted caspase-8 activation induced by treatment with TNF-related apoptosis-inducing ligand in cancer cells, potentially via dysregulation of mitochondrial dynamics and mitophagy." (PMID 34511600, 2022). "As a result, cancer cells regularly attempt to evade caspase-8-induced cell death through post-translational modifications, loss-of-function mutations of pro-apoptotic genes and the overexpression of anti-apoptotic genes or the expression of FLICE-like inhibitory protein long FLIPL." (PMID 36428594, 2022). "It is also valuable to study whether GSDMC/caspase-8-mediated pyrolysis has a role in other types of cancer." (PMID 35957895, 2022). "Also, in another study, the expression of GSDMC was found to be promoted by multiple antibiotics such as azithromycin in cancer cells, thereby activating caspase-8 to participate in pyrolysis and leading to the death of breast cancer cells." (PMID 35255915, 2022). "The presence of DRs and caspase 8 in cancer cells was crucial for AD-O51.4-induced apoptosis." (PMID 36387080, 2022). "Due to accumulating evidence for the involvement of TRAIL receptors and the subsequent activation of caspase-8 in ER stress-induced cell death in cancer cells, we next studied TRAIL-R2 receptor expression and the competency of pancreatic β cells to commit to TRAIL-R2 dependent cell death." (PMID 35075141, 2022).
cancer (continued). "It is hypothesized that Caspase-8 promotes cancer progression and resistance to therapy in some cancers." (PMID 35672443, 2022). "Among them, apoptosis-related genes, such as Casp6, Bak1 and Casp8 are up-regulated, suggesting that the GOD@POMs + laser treatment could cause cancer cells apoptosis." (PMID 36435848, 2022). "Similarly, the cellular capacity to activate caspase-8 in response to proteasome inhibition could provide a scenario in which targeted therapeutics that neutralize anti-apoptotic Bcl-2 family members could offer means to enhance cancer cell susceptibility to canonical intrinsic apoptosis." (PMID 34354257, 2022). "Co-occurrence of mutations that increase immunogenicity (e.g., BRCA1) with those enabling immune escape (e.g., CASP8) suggests a model of cancer progression where immune-mediated selection is a later event, in the setting of an otherwise immunogenic population." (PMID 35437329, 2022). "Notably, these cancer types only partially overlapped with those in which the CASP8/FLIP mRNA ratio was significant." (PMID 35086954, 2022). "However, it has been shown that ER stress-induced caspase-8 activation relies on a transcriptional upregulation of Tnfrsf10b in cancer cells that express notably higher amounts of TRAIL-R2." (PMID 35075141, 2022). "However, compared to BPH-1 cells, the 22Rv1 cancer cells showed increased cytopathic effect, higher induction of caspase-8 and -9, and extensive syncytia formation." (PMID 35631014, 2022). "This could favor cancer cells with defective CASP8, as CASP8-mutant cells are resistant to extrinsic apoptosis induced by cytotoxic T cells." (PMID 35437329, 2022). "Furthermore, the downregulation of caspase-8 expression or its catalytic activity have been shown to be beneficial for several cancers, but the molecular basis of the protease’s association with improved patient survival remains largely unexplored." (PMID 36428594, 2022). "LysRS can be secreted by cancer cells to induce inflammatory responses, whereas a more recent study showed a novel mechanism for the secretion of LysRS via exosomes or exosome-like extracellular vesicles from cancer cells, which is controlled by a caspase-8-dependent pathway." (PMID 35634293, 2022). "However, FADD-caspase 8 signaling complex (DISC) was previously shown to be inhibited by the expression of cellular FADD-like inhibitory protein (cFLIP) in cancer cells, a protein that is sensitive to cycloheximide (CHX)." (PMID 35970851, 2022). "To understand whether this process in cancer cells is an aberration of the physiological healing program, we have assessed the methylation status of important regulatory sequences in the caspase-8 promoter, namely the CpG loci and SP1 binding sites." (PMID 36112666, 2022). "Glycyrrhizin may exert effects and further inhibit cancer development through the CASP8-NF-kappa B pathway." (PMID 36193082, 2022). "Although PCA elevated caspase-3 activity in 5 cancer cells still, at the concentration of 2–8 μmol/L, PCA considerably enhanced caspase-8 activity, lowered intercellular adhesion molecule expression in cancer cells, and declined vascular endothelial growth factor production." (PMID 36247004, 2022). "Clues about the regulation of caspase-8 are reported in the context of cancer." (PMID 36112666, 2022). "A similar effect of Les-3331 on Casp-8 was shown in MDA-MB-231 cancer cells." (PMID 35456915, 2022). "We hypothesized that the block in caspase-8 RNA synthesis is achieved through promoter methylation, which is consistent with previous reports documenting the same phenomenon in a variety of cancer cells through the hypermethylation of regulatory DNA sequence." (PMID 36112666, 2022).